ACE (angiotensin I converting enzyme)
Diseases named in the same sentence as ACE in open-access papers (continued):
Sharing a sentence is not in itself a finding about the gene and the disease.
Hypertension (continued). "In conclusion, we produced a new miso with potent ACE inhibitory activity that reduced spontaneous and salt-induced hypertension." (PMID 30631160, 2019). "Perindopril arginine, selected as a control drug, is an ACE inhibitor used in the Hypertension in the Very Elderly Trial, a representative clinical study evaluating the effects of hypertension treatment in elderly patients older than 80 years." (PMID 31262348, 2019). "Comparative analysis of changes in oxidative stress parameters in COPD-only patients and patients with combined COPD + hypertension within one genotype of the ACE gene." (PMID 32025262, 2019). "Natural ACE inhibitors as alternatives with fewer side effects as compared to synthetic drugs have been a major interest for research in preventing hypertension." (PMID 31216636, 2019). "ACE inhibitory peptides derived from food protein sources are regarded as safer alternatives to synthetic antihypertensive drugs for treating hypertension." (PMID 31336853, 2019). "Majority of the cases were on treatment for diabetes mellitus, hypertension, and dyslipidemias; taking medications such as Glucophage, ACE inhibitors and statins." (PMID 30635365, 2019). "Perindopril is an angiotensin-converting enzyme (ACE) inhibitor indicated for the treatment of hypertension, congestive heart failure, and for the treatment of hypertensive and/or post-MI patients with stable coronary artery disease." (PMID 30535909, 2019). "Several plants in Liliaceae family from Allium were found as a potential effective remedy of hypertension possibly due to the inhibitory effects on ACE (Oboh, Ademiluyi, Agunloye, Ademosun, & Ogunsakin, 2018)." (PMID 30847157, 2019). "ACE inhibitors are recommended for patients with hypertension and stage A (NYHA class I) heart failure." (PMID 30808934, 2019). "ACE inhibition has become an established principle in the treatment of hypertension in clinical medicine (Messerli, Bangalore, Bavishi, & Rimoldi, 2018)." (PMID 31139400, 2019). "In patients with heart failure, the most frequent interaction was between ACE inhibitors and diuretics to treat hypertension." (PMID 31460618, 2019). "The biologically active potential of the digests was evaluated measuring in vitro antioxidant capacity by three complementary methods and enzyme inhibitory effects towards Angiotensin-I Converting Enzyme (ACE) related with the onset of hypertension." (PMID 31390766, 2019). "Expression of ACE is induced along with the induction of renin synthesis in the CD during Ang II-dependent hypertension." (PMID 31680980, 2019). "Adults prescribed oxybutynin were more likely to have a diagnosis of hypertension or obesity and to have filled a prescription for a diuretic, angiotensin-converting enzyme (ACE) inhibitor, or an older generation antihypertensive in the preceding 180 days." (PMID 31634354, 2019). "Clinical studies have shown that treatment with RAS component inhibitors (especially ACE inhibitor) in patients with hypertension improves cognitive function, in addition to blood pressure-lowering effects." (PMID 31739443, 2019). "Synergism among genetic variants in other components of the RAAS has already been reported, nevertheless, to our knowledge, this is the first study exploring the effect of the combination of ACE and ACE2 polymorphisms on hypertension susceptibility." (PMID 31430320, 2019). "Repressing ACE expression has been proved as an effective strategy in controlling hypertension, as its downregulation will inhibit the conversion of angiotensin I to angiotensin II." (PMID 30875817, 2019). "Treatment intensification to achieve control of hypertension by means of agents such as ACE inhibitors and spironolactone that act via the renin–angiotensin system is clearly warranted both to preserve renal function and reduce protein loss." (PMID 31461449, 2019).
Hypertension (continued). "Renin in turn transforms angiotensinogen into angiotensin I, which is then converted into angiotensin II by ACE, resulting in hypertension." (PMID 31379972, 2019). "The drugs related to this pattern were antithrombotic agents for cardiovascular prevention and ACE inhibitors for hypertension treatment." (PMID 30726245, 2019). "Captopril is a sulfhydryl ACE inhibitor initially used in the treatment of hypertension and heart failure, and is protective against retinopathy and nephropathy." (PMID 30591971, 2019). "Comparing with Angiotensin converting enzyme (ACE) rs4425 AA genotype, TT genotype was associated with hypertension risk (OR = 2.16, 95% CI: 1.17–4.00)." (PMID 31484569, 2019). "Chronic treatment of hypertension or heart failure very often includes an angiotensin-converting enzyme inhibitors (ACE-Is) or angiotensin receptor blockers (ARBs) as renin-angiotensin system inhibitors (RASi) treatments." (PMID 30836981, 2019). "The inhibition of ACE enzymatic activity on angiotensin I is one of the major challenges to combat hypertension-related disorders." (PMID 31336853, 2019). "Blockers of the classical angiotensin-converting enzyme (ACE)/angiotensin (Ang) II/angiotensin type 1 receptor (AT1R) axis are well-established drugs for the treatment of hypertension." (PMID 31810197, 2019). "ACE rs4425, ACE rs4337, ART rs129876 and CYP11B2 rs1912 polymorphism were associated with an increased risk of hypertension in mutant homozygous genotype." (PMID 31484569, 2019). "Bioactive peptides derived from marine resources have potential ACE inhibitory activity and are considered as therapeutic agents to combat hypertension." (PMID 31336853, 2019). "The difference of genotype frequencies among hypertension and normal groups were statistically significantat loci rs4425 (A/T) and rs4337 (G/C) in the ACE gene, at locus rs129876 (G/A) in the ATR gene and at locus rs1912 (C/T) in the CYP11B2 gene." (PMID 31484569, 2019). "Further, a large study (the Suita Study, Japan) which enrolled 14,200 individuals suggested a unique sex-specific effect of ACE on hypertension." (PMID 30333281, 2019). "Analysis of the available literature suggests the absence of studies on interrelationships between polymorphisms in the ACE and AGT genes and oxidative stress parameters in patients with comorbid COPD and hypertension." (PMID 32025262, 2019). "ACE inhibitors, e.g., captopril, are regularly used to treat hypertension, and other cardio-related diseases as an influencer of blood pressure." (PMID 31671730, 2019). "A previous study showed long-lasting activity of ACE inhibitors as hypertension agents in spontaneous hypertensive rat (SHR) brains." (PMID 31590451, 2019). "Among the 36 drugs from nine drug classes included for hypertension, α1-adrenergic receptor antagonists had the highest mean inflation-adjusted 28-day launch price (£36.50) followed by angiotensin converting enzyme (ACE) inhibitors (£35.00)." (PMID 31061053, 2019). "Licorice can interfere with cardiac medications, e.g., with drugs used in the treatment of hypertension such as angiotensin converting enzyme (ACE)-inhibitors." (PMID 31615045, 2019). "When test parameters of oxidative stress were compared, the most significant increase in RSO and 8-isoprostane levels was found in patients with comorbid COPD+hypertension, and the I/I genotype of the ACE gene (the difference compared with controls)." (PMID 32025262, 2019). "ACE inhibitors, especially perindopril, appear to be effective in reducing hypertension and enhancing cognitive protection by modulating brain RAS." (PMID 31739443, 2019). "Until now, most previous studies have focused on the association between ACE or ACE2 polymorphisms and hypertension individually." (PMID 31430320, 2019). "This study aimed to investigate the association between 4 polymorphisms in RAAS genes (i.e., rs1799752 (ACE), rs699 (AGT), rs5186 (AGTR1), and rs1799998 (CYP11B2)) and hypertension in a Thai population." (PMID 31511791, 2019).
Hypertension (continued). "The results obtained in this study have shown that elderly age, dyslipidemia and the combination of genetic polymorphisms of ACE and ACE2 were independent risk factors for hypertension in the sample analyzed." (PMID 31430320, 2019). "Prescriptions of ACE inhibitors/ARBs were associated with family history, CKD, hypertension, PCI, and the PFE system." (PMID 31170175, 2019). "Although nearly two-thirds of the adults with CKD had diabetes, hypertension, or prediabetes, rates of laboratory testing for albuminuria or proteinuria and of prescribing ACE inhibitors or ARBs were low." (PMID 31860111, 2019). "In conclusion, timely and effective antihypertensive therapy with ACE inhibitors for as short a period as 3 months was observed to produce significant improvements in cognitive performance compromised by early hypertension-related vascular damage." (PMID 31441902, 2019). "Several genes including WNK1, WNK4, Bp1, Bp2, AGT, and ACE were reported to be involved in hypertension." (PMID 30875817, 2019). "The general medical therapy for patients with coronary artery ectasia includes antiplatelet agents, β-blockers, ACE inhibitor, ARBs, CCBs and statins, especially if another indication is present (e.g., hypertension, dyslipidemia, diabetes mellitus)." (PMID 31382884, 2019). "ACE (angiotensin-converting enzyme) inhibitors are widely used for treating hypertension, myocardial infarction and renal failure." (PMID 31615765, 2019). "So far, there are no reliable data on the plausible relationship between the concentrations of hemorphins released in blood and the expression profiles of AT1R and ACE and its impact on the control of blood pressure and hypertension." (PMID 31708782, 2019). "In some patients with hypertension and diabetes mellitus, ACE inhibitors and ARBs are also indicated to prevent renal damage." (PMID 31337127, 2019). "One approach to addressing hypertension is the use of synthetic drugs to inhibit the activity of angiotensin I-converting enzyme (ACE)." (PMID 31208053, 2019). "One of the most famous examples of toxin-inspired pharmacological drugs is captopril, a drug for hypertension treatment that inhibits angiotensin-converting enzyme (ACE)." (PMID 31242582, 2019). "No obvious association was observed between these clinical and biochemical characteristics (age, BMI, Gender, hypertension, diabetes, WBC, HDL-c and FIB) and the ACE I/D polymorphism." (PMID 31873176, 2019). "Short- and long-term administration of VPH and its fraction VPH-I were found to attenuate hypertension mainly by inhibiting the ACE activity, besides their role in correcting the lipid disorder, reducing plasma glucose level and protecting from thrombosis." (PMID 30934709, 2019). "Previously ACE inhibitors were found ineffective as first-line medications for the management of hypertension in Africa, although the reason remained elusive." (PMID 30763326, 2019). "The son of the index patient (patient III-5), aged 42 years, developed swellings of the lips after he had started an angiotensin-converting enzyme (ACE) inhibitor for treatment of hypertension." (PMID 30809376, 2019). "We recommend using angiotensin-converting enzyme (ACE) inhibitors or angiotensin receptor blockers as first-line antihypertensive treatment in children with ADPKD who have hypertension and albuminuria (evidence level B; recommendation level moderate)." (PMID 31118499, 2019). "Secondly, the ACE II-A9570G, ACE-ID/DD and/or AGT-M235T polymorphism were associated with an increased risk factor for arterial hypertension in FSGS with fast progression to chronic kidney disease (CKD)." (PMID 30333281, 2019). "Among these, ACE inhibitors and ARBs have been proven to be clinically effective in the treatment of hypertension, as well as heart failure, by acting on the renin–angiotensin system, which acts as a main cause mechanism in cardiovascular disease." (PMID 31262348, 2019).
Hypertension (continued). "Plenty of synthetic drugs, such as captopril, that used in the treatment of hypertension were ACE inhibitors." (PMID 30847157, 2019). "In recent years, many plant components, Ocimum gratissimum extract, mango leaf Extract, Carica papaya extract, and mulberry leaf aqueous extract, had shown anti-hypertension effects through an inhibition of ACE activity." (PMID 31114496, 2019). "Less than 20 patients were on amlodipine with angiotensin converting enzyme inhibitors (ACE inhibitors) or angiotensin II receptor blockers (ARBs) for hypertension." (PMID 31372162, 2019). "The role of ACE and AGT gene polymorphisms in the pathogenesis of comorbid COPD and hypertension is the focus of the research community’s attention." (PMID 32025262, 2019). "Ten participants, four in the minoxidil and 6 in the placebo group had a previous history of cardiovascular diseases, and four were treated for hypertension (2 received ACE inhibitors in the minoxidil and 2 received Beta blockers in the minoxidil group)." (PMID 31138170, 2019). "Due to the difficulties in achieving controlled blood pressure in people with diabetes, ACE inhibitors or ARBs and a combination of antihypertensive agents are recommended treatments for patients with hypertension and comorbid diabetes." (PMID 31799289, 2019). "Pharmacological blockade of Ang II formation and AT1R-mediated actions with ACE inhibitors and ARBs, respectively, is commonly used for hypertension treatment in obese and type II diabetic patients due to their positive metabolic profile." (PMID 31262355, 2019). "In this study, we identified that the boiling water extract of corn silk exhibited anti-hypertension effects in SHRs via the inhibition of ACE, the target of anti-hypertensive drugs." (PMID 31100914, 2019). "Only one woman in labetalol group required admission on 5th postnatal day for uncontrolled hypertension and received an ACE inhibitor for blood pressure control." (PMID 31489020, 2019). "As to longer-term treatment, further prospective data are essential to determine the duration of ACE inhibition required for significant improvement in early hypertension-related vascular damage." (PMID 31441902, 2019). "A total of 59.8% of this cohort had hypertension, among which 70.8% were on treatment of an ACE inhibitor or angiotensin receptor blocker (ARB)." (PMID 31706298, 2019). "Our data showed that the boiling water extract of corn silk inhibited the ACE activity and exhibited anti-hypertension effects in SHRs." (PMID 31100914, 2019). "Captopril, enalapril, lisinopril, and benazepril are commonly used as effective synthetic ACE inhibitors and have been developed for treating hypertension." (PMID 31336853, 2019). "Inhibition of the angiotensin-converting enzyme (ACE) is established as one modern therapeutic approach to hypertension." (PMID 31683604, 2019). "The most important finding of the present study was that this newly manufactured miso with potent ACE inhibitory activity attenuated spontaneous hypertension in this model." (PMID 30631160, 2019). "The angiotensin converting enzyme (ACE) plays an important role in hypertension; therefore, inhibition of ACE in treatment of chronically elevated blood pressure is an important therapeutic approach." (PMID 31309069, 2019). "We also review the future prospects of ACE inhibitory peptides derived from marine organisms as therapeutic drugs to combat hypertension." (PMID 31336853, 2019). "In a rural Chinese population, the cigarette smoking index and ACE gene showed a low exposure-gene effect on essential hypertension with interaction indices." (PMID 30857519, 2019). "In Chinese Kazakh women, an interaction of ACE genotype and salt intake on hypertension was observed." (PMID 30857519, 2019). "Food sources of ACE inhibitors are of great interest, since individuals with hypertension can consume them as part of a healthy diet to reduce their high blood pressure." (PMID 30235793, 2018).
Hypertension (continued). "Synthetic drugs such as captopril, enalapril, benazepril, and other ACE inhibitors have been used clinically to prevent and treat hypertension." (PMID 30373231, 2018). "Knowledge of hypertension status was at 56 (27.7%) patients, 24 (44.4%) hypertensives were on treatment, and 19 (33.9%) were using ACE inhibitors/ angiotensin receptor blockers." (PMID 29750228, 2018). "The main agents used for treating hypertension (and their % use in subjects with hypertension) were: the diuretic, hydrochlorothiazide (38.6%); the ACE inhibitor, enalapril (45.3%); the calcium channel antagonist, adalat (25.6%)." (PMID 29953520, 2018). "ACE inhibitors (ACEIs) such as captopril (Cap) are predominantly used for the management of hypertension." (PMID 29765306, 2018). "In patients with AS and TBMN ACE inhibitors are recommended by the expert guidelines for the treatment of hypertension and proteinuria especially in individuals with genetic variants." (PMID 29946535, 2018). "Inhibition of enzymes in the RAS pathway, especially ACE, is regarded to be a potent therapeutic approach in the treatment of hypertension (Lin, Lv, & Li, 2012)." (PMID 30349677, 2018). "Angiotensin I-converting enzyme (ACE) plays a fundamental role in the management of hypertension as it coverts angiotensin I to the potent angiotensin II which is vasoconstrictor." (PMID 30581531, 2018). "An 89-year-old woman with a medical history for arterial hypertension, ischemic heart disease, heart failure, chronic atrial fibrillation developed ACE inhibitor-induced angioedema after 5 years of daily ramipril administration." (PMID 30075570, 2018). "The AF event rate was significantly lowered by an improved risk factor management like the usage of angiotensin-converting enzyme (ACE) inhibitors or angiotensin receptor blockers (ARBs) for hypertension control." (PMID 29313142, 2018). "Several studies linked the increased ACE concentrations with the DD genotype, CAD, hypertension, autoimmune diseases and acute respiratory distress syndrome." (PMID 30159092, 2018). "Sulfur-containing metabolites are crucial for the inhibitory activity against ACE, which catalyzes the reaction from angiotensin I to angiotensin II in the renin–angiotensin system and plays a major role in hypertension." (PMID 30477129, 2018). "The ACE inhibitors such as captopril, lisinopril, enalapril, ramipril and perindopril have been widely used clinically in the treatment of hypertension and myocardial infarction as well as diabetic nephropathy." (PMID 29476645, 2018). "Arterial hypertension, ischemic heart disease, heart failure, chronic atrial fibrillation and late onset ACE inhibitor-induced angioedema." (PMID 30075570, 2018). "Angiotensin-converting enzyme (ACE) inhibitors are one of the most used medication among patients with arterial hypertension." (PMID 30075570, 2018). "Contextually, the DF refer to the biopeptides specifically produced to act as ACE-inhibitors other than their primary role in nutrition and can be used in the management of hypertension." (PMID 29991723, 2018). "Among those with diagnosed hypertension, the most commonly prescribed medications were angiotensin-converting enzyme (ACE) inhibitors (39.6% of patients), β-blockers (34.5%), calcium channel blockers (29.7%), and thiazide diuretics (29.7%)." (PMID 29494332, 2018). "As a metabolite of arachidonic acid (AA), partly by CYP4F2 protein, 20-HETE induces the transcription of ACE (angiotensin-converting enzyme) gene through stimulating the NF-ΚB pathway and contributes to the pathophysiology of hypertension." (PMID 29426278, 2018). "For this reason, the JNC 7 and JNC 8 recommend that every diabetic who has hypertension must be started on ACE inhibitors/ARBs among other treatment options." (PMID 29750228, 2018). "The use of either ACE inhibitors or angiotensin receptor blockers (ARBs) among those who knew their hypertension status was only 19 (33.9%) subjects." (PMID 29750228, 2018).